EBI3 (Epstein-Barr virus induced 3)
Diseases named in the same sentence as EBI3 in open-access papers (continued):
Sharing a sentence is not in itself a finding about the gene and the disease.
tumor (continued). "Similarly, inoculation of b16 tumor cells in Ebi3-knockout mice showed enhanced anti-tumor immunity relative to wild-type mice and the metastatic potential of tumor cells were suppressed." (PMID 28794689, 2017). "Taken together, these results suggest that EBI3 may mediate a bidirectional reciprocal-regulation STAT3 signaling pathway to assist the tumor escape immune surveillance in CRC." (PMID 27247488, 2016). "To date, little is known about the role of EBI3 in tumor microenvironment." (PMID 27247488, 2016). "It is worth noting that EBI3 block was unable to reduce the expression of gp130 on CD45+CD3+CD8+TILs (date no shown) but able to reduce gp130 expression on CRCs or C26 cells generated tumor." (PMID 27247488, 2016). "EBI3 blocking peptide promoted antitumor cytotoxic T lymphocyte (CTL) response by inducing Granzyme B, IFN-γ production, and p-STAT3 expression and inhibited CRC cell proliferation and tumor growth to associate with suppressing gp130 and p-STAT3 expression." (PMID 27247488, 2016). "Metronomic CPA treatment also induced a core set of death-related genes that may be important for innate and/or adaptive immune activation by damaged tumor cells, including Sp110, Mx1, Mx2, Ebi3, Eomes, Tnfsf4, Gdf15, Ddx58, and Dhx58." (PMID 25952672, 2015). "Expression of EBI3 and p28 by tumor cells was detected in most cases (17/19 cases, 89%)." (PMID 24130734, 2013). "However the subunit alpha can also bind to the Epstein-barr virus-induced gene 3 (Ebi3) protein to form the IL-35, a cytokine known to promote tumor growth and metastasis by converting resting B and T cells into IL-10- and IL-35-producing regulatory B (Breg) and T (Treg) cells." (PMID 37435060, 2023). "IL-35 expression within the TME can promote primary tumor cell growth and metastatic colonization at a secondary site, signaling through a receptor composed of gp130 and IL-12Rβ2 to induce downstream Ebi3 and IL-12a transcription and the activation of a classical JAK-STAT signaling pathway." (PMID 34093586, 2021). "However, the exact mechanisms of EBI3 in CRC tumor microenvironment are not fully understood." (PMID 27247488, 2016). "Interestingly, positivity for EBI3 and p28 was observed in tumor cells." (PMID 24130734, 2013). "This inhibition promotes the secretion of immune-modulatory factors CXCL10, CXCL11, EBI3, and FLT3LG by tumor cells, thereby alleviating immunosuppression and enhancing CD8+ T cell recruitment into the tumor microenvironment and boosting antitumor immunity." (PMID 41293150, 2025). "Specifically, cytokines involved in tumor progression such as CXCL8, EBI3, and IL1RN were upregulated in the triculture samples compared to other conditions." (PMID 40056038, 2025). "Through in vitro and in vivo experiments, we disclosed that NCD upregulates the TIME-GES genes CXCL10, CXCL11, EBI3, and FLT3LG, promotes CD8+ T cell activation and tumor infiltration, thereby inhibiting the growth of TNBC." (PMID 41293150, 2025). "A β-subunit of IL-12 family member (EBI3) was confirmed to promote T- and B-cell differentiation through the gp130-STAT3 signal pathway and thereby playing a crucial role in inhibiting tumor cell proliferation and invasion." (PMID 37488455, 2023). "The administration of an EBI3 blocking peptide led to an antitumor cytotoxic T lymphocyte response and the inhibition of CRC cell proliferation in a tumor xenograft model." (PMID 33143318, 2020). "This concept is further supported by work in EBI3 and IL-27R KO mice demonstrating that IL-27 directly enhances Treg activity by inducing CD39 expression, resulting in tumor growth." (PMID 31681561, 2019). "The P35 antibody successfully immunoprecipitated EBI3 in PDAC tumour tissues and PDAC primary cell lines, and vice versa, whereas P28 and P40 antibodies immunoprecipitated much lower amounts of EBI3 and P35." (PMID 28102193, 2017).
tumor (continued). "In the process of tumour immune escape, Tregs can secrete TGF-β, IL-10, and IL-35 (Ebi3-IL-12α heterodimer), which downregulate antitumour immunity, suppress antigen presentation by DCs, CD4+ T helper (Th) cell function and generate tumour-specific CD8+ cytotoxic T lymphocytes (CTLs)." (PMID 32680511, 2020). "In GC, EBI3 and IL12A expression are strongly related to larger tumor size." (PMID 33064893, 2020). "It should be noted however that, when tumor rejection was seen in the absence of IL-35, achieved by Ebi3 KO in the tumor host, tumor-infiltrating T cells no longer expressed LAG3 and TIM3, but still expressed PD1, a common activation marker of T helper cells." (PMID 32983104, 2020). "Since these studies use EBI3 KO mice, these mice are lacking IL-27 and IL-35, thus potentiating a role for IL-30 in promoting Treg development and contributing to tumor progression." (PMID 31681561, 2019). "Of note, poorly or nondifferentiated tumor tissues showed higher levels of EBI3, IL-12p35, gp130, and p-STAT3 expressions than well or moderately differentiated tumor tissues." (PMID 27247488, 2016). "Then, we isolated CRC cells and tumor infiltrating lymphocytes (TIL) from 10 CRC patients tissues to assess the Granzyme B, IFN-γ, EBI3, IL-27p28, and IL-12p35 production and proliferation of TILs, Tregs after coculture with autologous CRC cells blocked by EBI3 blocking peptide." (PMID 27247488, 2016). "However, when tumor-bearing animals receive an adoptive transfer containing wild-type CD8+ T cells and Ebi3−/− CD4+ T cells, the growth of these tumors was reduced by approximately 50%." (PMID 24151492, 2013). "The correlation between elevated levels of EBI3 and p35 rather than p28 may hold potential information to how a tumor is able to influence the TME cytokine profile to promote tumorigenesis." (PMID 31681561, 2019). "Similarly, EBI3-positive cells in interfollicular areas or tumor infiltrates were not recognized by 15k8D10 mAb." (PMID 31316915, 2019). "Together, these results suggest that EBI3 maybe does not promote Tregs proliferation or mediate TILs proliferation to inhibit CTLs response in tumor microenvironment." (PMID 27247488, 2016). "Here, we further demonstrated EBI3 not only promoted CRC cell proliferation through the gp130/Stat3 axis, but also restrained tumor infiltrating Granzyme B+ CTLs and IFN-γ+ CTLs production to promote tumor growth in CRC by EBI3 blocking peptide in vitro and in vivo." (PMID 27247488, 2016). "Of note, our previously study showed EBI3 association with IL-12p35 to promote CRC progression may recruit Treg cells and other immunosuppressive cells into the tumor microenvironment, but the exact mechanisms are not fully understood." (PMID 27247488, 2016).
infection (27 papers, 2010 to 2024). The state of being infected such as from the introduction of a foreign agent such as serum, vaccine, antigenic substance or organism. "In EBi3-/- mice, infection caused an increase in DNA demethylation and analyzing EBi3-/-C versus EBi3-/-I we can see that TET1 plays the major differences observed in S2, but TET2 and TET3 also increased strongly their expression values." (PMID 32078636, 2020). "The production of IL-4 and IL-13 was higher in spleen cells of infected Ebi3-deficient mice on day 7 post-infection, which probably generated an ideal microenvironment required to the differentiation of alternatively activated macrophages." (PMID 29033934, 2017). "We found that IL-10 production was significantly reduced in the myocardium of Ebi3-deficient mice compared to WT mice at day 15 after infection." (PMID 29033934, 2017). "Unexpectedly, the number of classical CD4+Foxp3+ Tregs producing IL-10 was similar in the cardiac tissue of Ebi3-deficient and WT mice at day 15 after infection, suggesting that Ebi3 was unable to promote the development of classical Tregs." (PMID 29033934, 2017). "We found increased number of IFN-γ producing CD4+ T cells in the cardiac tissue and spleen of Ebi3-deficient mice compared to WT counterparts 15 days after T. cruzi-infection." (PMID 29033934, 2017). "In vivo findings revealed that mice deficient for Ebi3, a subunit of IL-27, were extremely susceptible to infection with 103 trypomastigote forms of T. cruzi, a quantity that was not lethal to WT mice." (PMID 29033934, 2017). "It was observed that Ebi3-deficient mice exhibited an increased heart parasitism with concomitant alongside increased blood levels of CK-MB at day 15 of infection, indicating intense myocardial damage." (PMID 29033934, 2017). "Th1, Th2, and Th17 cytokines were augmented in the spleen of Ebi3-deficient mice during the acute phase of the infection with T. cruzi (7 d.p.i)." (PMID 29033934, 2017). "The anti-inflammatory genes CCL4 and EBI3 were induced earlier (5 dpi) upon infection with the wt isolate." (PMID 35215144, 2022). "While there was also no significant increase in the expression of the IL-27 subunit EBI3 during the infection, the gene was well expressed in MDSCs from the control and infected neonates." (PMID 34208904, 2021). "It was also recently demonstrated that the infection of macrophages with virulent Mycobacterium tuberculosis increases intracellular EBI3 expression via its binding to eukaryotic translation elongation factor 1-α1 (eEF1A1), probably to facilitate infection." (PMID 34603342, 2021). "EBI3 expression is constitutively highest in the placenta but is inducible by infection with EBV in B lymphocytes and activation through Toll-like receptors (TLRs) in dendritic cells (DCs)." (PMID 34603342, 2021). "• P28 expression is increased in infected tissue at week two post-infection. • EBI3 expression becomes detectable in infected tissue at week five post-infection." (PMID 32849534, 2020). "Studies on different subunit chains of IL-12 family revealed that p35 chain of IL-12 and EBI-3 were gradually up regulated, while p28 of IL-27 and p40 of IL-12 remained restricted during the course of infection." (PMID 31031744, 2019). "The upregulation of IL6ST and EBI3 was less pronounced after infection compared to that of IL8 and IL23A." (PMID 24069393, 2013). "Collectively our findings demonstrate that the immune system produces IL-12 to suppress bacterial growth upon infection while Lm utilizes another host immune component, EBI3, to escape immune surveillance." (PMID 24068935, 2013). "Gene expression analysis demonstrated a strong upregulation of IL23A (encodes p19) by infection, whereas IL23R, Epstein–Barr virus-induced gene 3 (EBI3), IL6ST, IL12A, and IL27RA were found to be expressed, but not regulated, or to a lesser extent." (PMID 24069393, 2013).
infection (continued). "Because EBI3 is a subunit of the heterodimeric cytokine, IL-27, we tested the ability of serum IL-27 protein concentrations to predict infection." (PMID 23107287, 2012). "Similarly, we found that the expression of liver EBI3 protein remained elevated after infection but decreased in the fibrogenesis phase compared with the inflammatory stage." (PMID 37480105, 2023). "We found that the IL-35’s subunits p35 and EBI3 expressions, serum IL-35 level as well as IL-35-producing iTr35 cell subset were concurrently increased in the Mtb-infected mouse spleen at 4 or 8 weeks post-infection, especially in 8 week infected mice." (PMID 35434368, 2022). "To verify the relationship between IL-27 and liver injury in a CLP-induced severe infection mouse model, we first detected IL-27 levels in serum by ELISA and the expression levels of EBI3 and P28 (subunits of IL-27) in the liver tissue by q-PCR and Western blot." (PMID 33564275, 2021). "• CD11c+ DCs express P28 and EBI3 in draining lymph nodes at 24 h post-infection." (PMID 32849534, 2020). "Interestingly, our analysis revealed a significant positive correlation between IL23A and EBI3 after infection with P1 strain only." (PMID 24069393, 2013). "In our study, the differentially regulated epithelial-derived expression of IL23A and EBI3 with their receptors upon infection with different strains of H. pylori suggests a possible biological role for these molecules either alone or in combination with other molecules." (PMID 24069393, 2013). "Remarkably, IL23A was positively correlated with EBI3 after infection with P1 strain only (P<.05)." (PMID 24069393, 2013). "Moreover, IL-4 and IL-13, key cytokines associated with M2 macrophages, were not modulated by the infection or the absence of Ebi3 in the hearts of animals." (PMID 29033934, 2017). "We also evaluated whether Ebi3 could promote classical Tregs and/or Tr1 cells during the infection." (PMID 29033934, 2017). "CD11c+ DCs express both IL-27 subunits, including p28 and EBI3, in the draining lymph nodes of L. major-infected C57BL/6 mice at 24 h post-infection." (PMID 32849534, 2020). "L. major lysate-stimulated lymphocytes from EBI3−/− mice secrete fewer IFN-γ and high IL-4, IL-10, and IL-13 as compared to the lymphocytes from the control mice on the second and third week post-infection." (PMID 32849534, 2020). "The results from an in-vitro analyses indicate that the expression of both IL-27 subunits, including p28 and EBI3, is augmented in L. amazonensis-infected macrophages from C57BL/6 mice measured at 4 hours after infection." (PMID 32849534, 2020). "Our gene expression analysis revealed induction of EBI3 by H. pylori co-infected gastric cell lines, and correlation with IL23A expression after P1 strain infection." (PMID 24069393, 2013). "In contrast, no changes were observed in Ebi3 mRNA transcripts were observed during infection, with only a slight reduction at a later time point." (PMID 38966644, 2024). "Our results revealed increased DNA demethylation during infection of EBi3-/- mice, while wild-type mice do not altered the methylation during infection." (PMID 32078636, 2020). "Results showed that IL-23, EBI-3 (IL-27 beta subunit), IL-12p40, IL-12p35, IFN-γ, IL-6, and IL-10 mRNA expression were all increased both in the liver and in the spleen during PbNK65 hrfΔ infection as compared to WT infection." (PMID 28831137, 2017). "Although the infection upregulated the gene expression of markers expressed on alternatively activated macrophages (Arg1 and Chi3l3), Ebi3 did not have any impact on their expression in the heart of 15-day-infected animals." (PMID 29033934, 2017). "Although the infection did not increase EBI3 mRNA expression in the BM and spleen of both WT and IFN-γ-deficient mice, intriguingly, the infection greatly enhanced p28 mRNA expression in WT mice but failed to enhance it in IFN-γ-deficient mice." (PMID 26991425, 2016).
infection (continued). "While the expression of EBI3 remained always comparable to basal levels, IL-27p28 expression was significantly upregulated but only in DCs from BALB/c 24 h after infection (p ≤ 0.05)." (PMID 27867384, 2016). "Co-expression of p35 and EBI3 observed 8 hours post-infection however, does not preclude IL-35 expression." (PMID 21085698, 2010). "The majority of individuals expressed p19, p35, p40 and EBI3 in response to infection, however, amongst the donors tested, none showed induction of the p28 subunit (n = 7; data not shown)." (PMID 21085698, 2010). "Interestingly, lymphocytes and specifically NK and T cells recruitment to the bronchoalveolar space (BAL), but not lung tissue/parenchyma were significantly reduced in Ebi3−/− mice early point of infection." (PMID 30899058, 2019). "In contrast Ebi3 expression was not dramatically upregulated after infection." (PMID 29593047, 2018). "Overall, the absence of Ebi3 during the infection with T. cruzi led to the production of Th2 cytokines, which promoted parasite growth, and the induction of Th1 and Th17 immune responses, which in turn aggravated the inflammation in the liver and heart of infected animals." (PMID 29033934, 2017). "While Ebi3 was constitutively expressed and not significantly upregulated in the lungs and other organs, Il-27p28 expression displayed a pronounced peak on day 7 post-infection (d.p.i.), two days after the peak of the viral load." (PMID 24809349, 2014). "However, whether the absence of the EBI3 subunit has an impact early after infection was not addressed in this work." (PMID 27867384, 2016). "In contrast, no significant changes were observed for the expression of IL27p28 and EBI3 mRNA in the animals, irrespective of CD4 count or infection status." (PMID 38966644, 2024). "The percentages of IFNγ-producing NKT cells and NK cells in EBI3−/− mice were comparable to those from wild-type mice, indicating that there is no significant role of EBI3 in the induction of IFNγ from NK and NKT cells after Lm-Ova infection." (PMID 24068935, 2013). "We observed significantly less bacterial burden in the livers of EBI3−/− mice compared with those from wild-type, indicating that EBI3 is not required for the host defense against the infection." (PMID 24068935, 2013).